EPCAM (epithelial cell adhesion molecule)
Diseases named in the same sentence as EPCAM in open-access papers (continued):
Sharing a sentence is not in itself a finding about the gene and the disease.
prostate carcinoma (continued). "EpCAM-targeted and ferumoxide labeled NK cells demonstrated substantial decreased T2* signals in EpCAM-positive prostate cancers than ferumoxide labeled nontargeted parental NK-92 cells." (PMID 26394751, 2015). "This indicates that PBLs targeting EpCAM are able to perform significant cytotoxic activities against PC3 cells and thus may be an effective therapeutic approach for prostate cancer." (PMID 25636521, 2015). "Therefore, PSMA, EpCAM and VEGF can be used as targets for the bioimaging of recurrent prostate cancer after EBRT to exclude metastatic disease and/or to plan local salvage therapy." (PMID 24727373, 2014). "Furthermore, EPCAM, which mediates cell adhesion, and ITGB4, an integrin that can regulate cellular growth and movement, were downregulated in 3xR cells, and both have been shown to be overexpressed in prostate cancer and facilitate metastasis." (PMID 37870957, 2023). "Considering that EPCAM deletions have a relatively high frequency in MMR-d tumors (21.4% in MMR-d metastatic tumors), we presume that the prevalence of Lynch syndrome in MMR-d prostate cancer may be higher than previously thought." (PMID 36675550, 2023). "Additionally, regardless of prostate cancer stage, the combination of EpCAM and vimentin antibodies proved to be more effective in isolating CTCs than using either EpCAM or vimentin antibodies alone." (PMID 37345161, 2023). "Therefore, with the aim to quantitatively measure their EpCAM expression level, we have identified prostate cancer CTCs in leukapheresis-derived patient samples using non-EpCAM markers." (PMID 37055551, 2023). "Another potential limitation is that undifferentiated prostate cancer cells (i.e., neuroendocrine prostate cancer) may not be captured by EpCAM antibody." (PMID 37477521, 2023). "EpCAM is a membrane glycoprotein highly expressed in the majority of carcinomas; accordingly, this is the first and only clinically validated U.S. Food and Drug Administration (FDA)-cleared blood test for detecting CTCs in patients with metastatic breast, colorectal, or prostate cancer." (PMID 36672660, 2023). "Therefore, the high renal uptake should not appreciably affect the accuracy of EpCAM imaging in oligometastatic prostate cancer using radiometal-labeled Ec1." (PMID 34298801, 2021). "Indeed, by knocking down PHF19L, we observed significant induction of multiple genes known to promote changes in cytoskeleton and adhesion, extracellular matrix remodeling, invasion, and metastasis in prostate cancer (including SOX9, SOX4, MMP1, PLAU, EPCAM, CXCR4, LOX, and MET)." (PMID 32155117, 2020). "However, clinical trials based on EpCAM-CART and EpCAM-antibody immunotherapy for prostate cancer are still absent so far." (PMID 32183880, 2020). "Enumeration of not only EpCAM+CTCs but also EMT+CTCs, circulating macrophages and pairs/clusters of cells may be a viable option for characterization of tumor aggressiveness in human prostate cancer patients." (PMID 27780930, 2016). "However, current often epithelial cell adhesion molecule (EpCAM)-based detection methods, commonly used on peripheral blood (PB) samples, are limited to a few cancers with higher CTC numbers such as breast and prostate cancer, or very rare cases of patients with exceptionally high CTC numbers." (PMID 38720314, 2024). "First, the fate of disease outcome in non-progressed patients that had higher CTC count or EPCAM/PSMA expression is not known and takes many years to ascertain in the case of prostate cancer." (PMID 40672470, 2025). "While EpCAM is regularly utilized to detect cancer cells in the circulation of prostate cancer patients, the requirement of cells to undergo EMT prior to metastasis suggested that neither EpCAM nor E-cadherin would be expressed on CSCs." (PMID 28690641, 2017). "Expression analysis showed higher detection rates of EPCAM and KRT transcripts in single cells from non-metastatic prostate cancer patients than in the controls." (PMID 26378808, 2015).
prostate carcinoma (continued). "Currently, there is no knowledge about the expression of PSMA, EpCAM, VEGF and GRPR in locally recurrent prostate cancer after brachytherapy or external beam radiotherapy." (PMID 24727373, 2014).
colon carcinoma (188 papers, 2000 to 2025). "We investigated the prevalence of LS, frequency of pathogenic variants in MMR/EPCAM genes, and genotype-phenotype correlation in 31 individuals; 20 were affected with colon cancer and 11 were unaffected." (PMID 36421850, 2022). "Analysis in endometrial and colon cancer cell lines demonstrated that EGF treatment caused EpCAM cleavage by γ-secretase." (PMID 34209658, 2021). "It is worth mentioning in support of the present finding that both molecules were found in the proteomic profile of a sub-population of EpCAM-associated exosomes that are released from LIM1863 colon carcinoma cell-derived organoids." (PMID 24911657, 2014). "Epithelial cell adhesion molecule was discovered as one of the first tumour-associated antigens by immunising mice with human colon cancer cells followed by analysis of tumour-specific monoclonal antibodies." (PMID 16404366, 2006). "Our findings illuminate the molecular mechanisms underlying EpCAM signaling promotion of colon cancer metastasis, further suggesting that the combination of EpAb2-6 and crizotinib may be an effective strategy for treating cancer patients with high EpCAM expression." (PMID 37543570, 2023). "The epithelial cell adhesion molecule (EpCAM) is another target for drug delivery, as it is a dominant surface antigen in human colon carcinoma." (PMID 40650240, 2025). "Identification of the DREAM transcriptional repression complex as a mediator of the differential response observed in EpCAM+/CD44+/CD166+ as compared to EpCAM+/CD44neg/CD166neg colon cancer cells following in vivo chemotherapy with irinotecan (CPT-11)." (PMID 39896677, 2025). "A notable finding is the synergistic effect observed in a human colon cancer model when combining Regorafenib with CAR-NK cells that target the epithelial cell adhesion molecule (EpCAM)." (PMID 40650066, 2025). "Target genes of this pathway, including CD44, CD133, Lgr5, EpCAM and c-Myc, are frequently used as markers of colon cancer-initiating cells." (PMID 40259095, 2025). "Specific molecular markers carried by exosomes (e.g., EpCAM, CD44, CD133, ALDH1) are considered to have potential as early diagnostic markers for colon cancer." (PMID 40277521, 2025). "EpCAM was expressed not only in the majority of breast and colon cancer tissues but also in some normal tissues." (PMID 40792441, 2025). "For the overexpression of EpCAM, the membrane protein of colon cancer-derived exosomes, we chose EpCAM aptamer for specific capture to achieve rapid detection of colon cancer-derived exosomes." (PMID 40277521, 2025). "EpCAM CAR-T cells effectively induce apoptosis in colon cancer cells and enhance the secretion of cytokines IL-2, IFN-γ, and IL-6, which play antitumor roles in immunotherapy by modulating immune responses." (PMID 39996844, 2025). "With remarkable sensitivity and specificity, the platform enables colon cancer detection by expression of the surface-specific membrane protein EpCAM within 10 min." (PMID 40277521, 2025). "We focused on colon cancer considering the strong EpCAM overexpression in this tumor type, but consider the findings of this proof-of-concept study as extrapolatable to virtually all EpCAM-expressing cancers." (PMID 37642704, 2024). "Immunofluorescence staining validated the characteristics of both organoids and fibroblasts, showing high expression of epithelial cell markers (EPCAM), colon cancer markers (CK20), proliferation markers (KI67), and fibroblast markers (VIM, SMA)." (PMID 38921017, 2024). "The extracellular domain of EpCAM stimulates proliferation of colon cancer cells, and this effect is inhibited by an EGFR inhibitor." (PMID 39594667, 2024). "The patient’s maternal grandfather was diagnosed with colon cancer at age 60 and was confirmed to have a germline EPCAM deletion." (PMID 38467830, 2024).
colon carcinoma (continued). "EGFR activation induced by the extracellular domain of EpCAM promotes cell migration of the colon cancer cells and this effect is abolished in cells treated with an EGFR inhibitor." (PMID 39594667, 2024). "In this study, we detected CTCs (CD45 [-], pan-CK [+], EPCAM [+]) from plasm samples of 9 colon cancer patients." (PMID 36776873, 2023). "Not only high- but also low-affinity anti-EpCAM fully human mAbs showed clear cytotoxicity against the human colon cancer cell line HCT116, which is a well-known EpCAM-expressing line." (PMID 36918661, 2023). "Treatment with anti-EpCAM mAb EpAb2-6 reduced colon cancer progression and metastasis, and importantly, it improved the survival of mice in orthotopic tumor and metastasis models." (PMID 37543570, 2023). "There is data suggesting that adoptive chimeric antigen-receptor-modified NK-cells transfected with EpCAM gene selectively targets EpCAM-expressing colon cancer cells with a release of interferon (IFN)-γ, perforin and granzyme-B and specific cytotoxicity." (PMID 37533952, 2023). "Our results show that EpCAM knockout attenuates phosphorylation of HGFR in colon cancer cells, and the cell growth and migration capacities in EpCAM knockout HCT116 cells were significantly reduced compared to wild-type cells." (PMID 37543570, 2023). "Lgr5, ALDH1, and EpCAM also play a crucial role in the maintenance of CSCs and are potential therapeutic targets for colon cancer." (PMID 37639070, 2023). "EpAb2-6, a new EpCAM neutralizing antibody, exhibited antitumor effects via inhibiting the nuclear translocation of EpICD/β-catenin complexes and inducing apoptosis in colon cancer cells." (PMID 36369033, 2022). "Zhou and colleagues noted the high expression of EpCAM in colon cancer and its correlation with lower survival rates in 50 tissues by immunohistochemistry." (PMID 35016698, 2022). "Epithelial cell adhesion molecule (EpCAM) was initially identified as an antigen expressed on colon carcinoma cells that induced a humoral response in mice." (PMID 34693227, 2021). "Our results showed that EpCAM is not only expressed by colon tumors, but also a potential biomarker for CRC-derived EVs." (PMID 34155195, 2021). "Another study showed the efficacy of atovaquone on EpCAM+CD44+ HCT-116 human colon cancer stem cells under hypoxia." (PMID 33562088, 2021). "Studies have also shown that the EpCAM extracellular domain can promote colon cancer cell migration, proliferation, and tumor growth by activating EGFR and downstream ERK1/2 signaling." (PMID 34790117, 2021). "EpMab-16 (mouse IgG2a) for EpCAM also demonstrated significant antitumor activity against colon cancer xenograft models, and oral squamous cell carcinomas." (PMID 34013368, 2021). "In colon cancer, EpCAM served as a CSC marker and was shown to be upregulated during signaling that promotes EMT." (PMID 34209658, 2021). "EpCAM is a tumor-related antigen first found in colon cancer tissue that is one of the main surface antigens of human colon cancers." (PMID 34790117, 2021). "EpCAM in colon cancer shows a much higher number of transcripts per million than in normal colon tissue." (PMID 34790117, 2021). "It is unclear to what extent the CETC detected in the study are related to the development of colon cancer as EpCAM used in our method is also overexpressed in colon cancer." (PMID 34590615, 2021). "Increased EpCAM expression occurred with other CSC markers in chemotherapy resistant LoVo colon cancer cells, which was mediated by CXC ligand signaling." (PMID 34209658, 2021). "EPCAM is frequently overexpressed in tumor cells, while its suppression is considered a new approach for the treatment of colon cancer." (PMID 34440702, 2021). "In the colon carcinoma cell lines with high EpCAM expression levels, the initial stimulation provided by the bispecific antibody was efficiently enhanced by all three costimulatory fusion proteins targeted to highly and moderately expressed EGFR." (PMID 32504247, 2020).
colon carcinoma (continued). "EpAb2-6 induces apoptosis, inhibits tumor growth in mouse models, and represses EpCAM cleavage to form the signaling moiety EpICD in pancreatic and colon carcinoma cells." (PMID 32507912, 2020). "The epithelial cell adhesion molecule (EpCAM) has first been described in 1979 as a humoral antigen expressed on colon carcinoma cells." (PMID 32507912, 2020). "In colon cancer cell lines, the expression of EpCAM enhanced the transcription of reprogramming factor genes c-Myc, Oct3/4, Sox2, and Nanog, and the EMT regulators Snail and Slug through EpICD signaling." (PMID 32507912, 2020). "Interactions between ADAM 10 and EpCAM in the tetraspanin web of human colon cancer cells were reported before EpCAM RIP." (PMID 32507912, 2020). "Clinically, Solitomab has demonstrated efficacy in EpCAM-positive colon cancer with gastrointestinal toxicity as a significant on-target side effect." (PMID 32438548, 2020). "Noteworthy, FGS of human colon tumors targeting the EpCAM glycoprotein resulted in excellent tumor localization despite relatively low TBRs of around two." (PMID 32780212, 2020). "A positive correlation is found between the expression of EpCAM and canonical Wnt signaling in colon cancer patient tissues, further indicating EpCAM signaling crosstalk with the Wnt pathway." (PMID 33374714, 2020). "Abnormal levels of epithelial cell adhesion molecule (EpCAM)+CD4+ T cells were observed in colon cancer patients." (PMID 33135337, 2020). "Our current study documents specific alternations of SL metabolism in epithelial EpCAM+ cells isolated from colon tumor tissue, which only partly overlap with gene expression changes detected in total colon tumor tissue samples." (PMID 31801289, 2019). "Among the cell adhesion molecules, epithelial cell adhesion molecule (EpCAM) is a pleitropic molecule that is highly expressed in a variety of carcinomas, especially in colon cancer, and is an immunotherapeutic target for several malignancies." (PMID 30289336, 2019). "Treatment with Rottlerin resulted in decreased expressions of EpCAM, E-cadherin, and claudin-3 both at mRNA and protein levels in all colon cancer cells." (PMID 30289336, 2019). "In human colon cancer cells, EpCAM has been suggested to regulate tight junctions by degradation of selected claudins." (PMID 31332522, 2019). "Our results showing the elevated expression of claudin-1, −3 and −4, EpCAM, E-cadherin in colon cancer were consistent with earlier studies." (PMID 30289336, 2019). "In colon carcinoma cells, EpEX induced mild proliferation and regulated proteolysis of intact EpCAM molecules through the activation of ADAM17 and γ-secretase." (PMID 30261040, 2018). "Work by Lin and colleagues in colon cancer cells demonstrated a function of EpCAM in the activation of pluripotency genes and EMT regulators, which is contradictory to our findings." (PMID 30261040, 2018). "It is of interest to note that in all the studies related to the use of CD133 and CD44 as markers for the identification and isolation of colon cancer stem cells, the expression on these cells of EpCAM was noted." (PMID 29652830, 2018). "Immune effects, including cytokine release and cytotoxicity of the CAR-NK-92 cells against EpCAM-positive colon cancer cells, were evaluated in vitro." (PMID 30410941, 2018). "Dot plots of side scatter versus EPCAM expression in colon-cancer cells showed that side-scatter properties of the cells changed with storage time, whereas EPCAM expression remained stable." (PMID 28975085, 2017).
colon carcinoma (continued). "It must be noted that Panorex was retrieved from the German market in 2000 and the actual benefit of this particular anti-EpCAM antibody was eventually refuted in a large cohort of patients suffering from stage III colon cancer." (PMID 28531111, 2017). "We next optimised the appropriate concentration of beads for magnetic separation by testing a concentration range of anti-EpCAM magnetic beads in SW480 colon tumour cells." (PMID 27711186, 2016). "To confirm the apoptosis-promoting effect of TSLP on primary colon cancer cells, we FACS sorted EpCAM+ cells from tumor tissues from patients with colon cancer and treated them with TSLP (100 ng/ml) for 48 h." (PMID 26919238, 2016). "EpCAM was first described as an antigen in colon carcinoma cells and is involved in the regulation of normal, malignant, and stem-cell phenotypes." (PMID 25477371, 2015). "MAb17-1A, a low affinity monoclonal antibody against EpCAM, is successfully used in Germany for breast and colon carcinoma therapy and CD3/17-1A, a bispecific scFv, is demonstrated to have cytotoxicity to EpCAM-positive tumor cells in vitro." (PMID 25960617, 2015). "In contrast, decreased EpCAM was demonstrated to closely correlate with progression, budding and metastasis of both breast and colon cancers." (PMID 26718583, 2015). "The aim of the study was to investigate the commonly used epithelial specificity, CD326/EpCAM, and the metastatic colon cancer cell marker, CD26/DPPIV." (PMID 25624884, 2015). "The combined expression levels of Aldh1, survivin, and EpCAM as strong independent prognostic factors for survival and tumor recurrence in colon cancer patients reflect tumor aggressiveness." (PMID 25889770, 2015). "Colon cancer cells exhibit the highest frequency of high-level EpCAM expression of any cancer, with frequency >90% for any subgroup." (PMID 26317650, 2015). "Together, these findings suggest that EpCAM is required for the survival of CTCs in cases of colon cancer." (PMID 26317650, 2015). "Such a high frequency of EpCAM expression on CRC at all stages of the disease makes colon cancer an ideal indication for anti-EpCAM-based therapies." (PMID 26317650, 2015). "For capture of exosomes in supernatants of colon cancer cell lines, anti-A33 Ab- coated Dynabeads or anti-EpCAM Ab-coated microbeads have been used prior to proteomics-based analyses." (PMID 25093329, 2014). "Protocol optimization was performed using breast and colon cancer xenograft tissues and fluorescently labeled aptamers or the EpCAM antibody 323/A3." (PMID 23460885, 2013). "The epithelial cell adhesion molecule (EpCAM, CD326) is a transmembrane glycoprotein originally discovered as a colon carcinoma-associated antigen." (PMID 23110550, 2012). "CD133+ cells, currently one of the best markers to characterize colon cancer stem cells and an independent prognostic marker that correlates with low survival, are positive for EpCAM." (PMID 22304365, 2012). "CD133+ cells, currently one of the best markers for the characterization of colon cancer stem cells and an independent prognostic marker that correlates with low survival, are positive for EpCAM." (PMID 22811761, 2012). "Although CD133, CD44, EpCAM were used extensively as cell surface markers for colon cancer stem cells, there were still doubts on these cell surface markers." (PMID 22745705, 2012). "The three different colon cancer cell lines displayed high (HT29) to medium (Caco2) to low (SW480) EpCAM mRNA levels in vitro as determined by qPCR." (PMID 22590529, 2012). "Colonospheres generated under present conditions from the three different colon cancer lines show increased expression of colon CSCs markers along with pan-epithelial marker EpCAM, when compared with the corresponding parental cells." (PMID 20691072, 2010). "CD133+ colon cancer cells include EpCAM hi/CD44+ cells, whereas the relationship between CD133+ subset and Lgr5+ subset is unclear." (PMID 19583834, 2009).